MDM4 (MDM4 regulator of p53)
Diseases named in the same sentence as MDM4 in open-access papers (continued):
Sharing a sentence is not in itself a finding about the gene and the disease.
oligodendroglioma (2 papers, 2012 to 2022). A well-differentiated (WHO grade II), diffusely infiltrating neuroglial tumor, typically located in the cerebral hemispheres.
thyroid cancer (2 papers, 2020 to 2021).
thyroid tumor (2 papers, 2009 to 2017). A benign or malignant neoplasm affecting the thyroid gland. "MDM4-211 is a variant of human MDM4 identified in a thyroid tumor cell line." (PMID 19721810, 2009).
acute kidney injury (1 paper, 2022). Sudden and sustained deterioration of the kidney function characterized by decreased glomerular filtration rate, increased serum creatinine or oliguria. "The expression of ESM1 and RALYL were markedly increased in control samples, while EHBP1L1, FBXW4, MDFI, and MDM4 were markedly increased in acute kidney injury samples." (PMID 36313991, 2022). "Six hub genes (MDFI, EHBP1L1, FBXW4, MDM4, RALYL, and ESM1) were identified as potentially predictive of an acute kidney injury." (PMID 36313991, 2022).
anemia (1 paper, 2012). A reduction in the number of red blood cells, the amount of hemoglobin, and/or the volume of packed red blood cells. "The panel included retinoblastoma binding protein 9 (RBBP9), Caspase recruitment domain family 11 (CARD11), Fanconi anemia complementation group c (FANCC), double minute 4 (MDM4), and breast cancer 1 (BRCA1)." (PMID 22859999, 2012).
autoimmune disease (1 paper, 2021). A disorder resulting from loss of function or tissue destruction of an organ or multiple organs, arising from humoral or cellular immune responses of the individual to their own tissue constituents. "Using IHC, mdm4 staining was negative in epithelial-like cells located in the medulla for the normal thymus tissue and tumor tissues without autoimmune disease." (PMID 35070964, 2021).
bone marrow failure (1 paper, 2023).
bone marrow failure syndrome (1 paper, 2023). "Evidence for this was already obtained in a familial syndrome of defective telomere maintenance caused by a MDM4 mutation, and it will be important to determine if this may also apply to other bone marrow failure syndromes caused by mutation in other genes." (PMID 37834388, 2023).
calcium oxalate kidney stones (1 paper, 2024). "Since it may be a therapeutic target for ferroptosis in calcium oxalate kidney stones, we plan to conduct some experiments to overexpress LAMP2 and MDM4 genes in HK-2 cells to determine the effects of these genes on the cellular response to ferroptosis." (PMID 38536018, 2024).
Cerebral ischemia (1 paper, 2025). Restriction of arterial blood supply to the brain associated with insufficient oxygenation to support the metabolic requirements of the tissue. "Notably, lncRNA FTX inhibits ferroptosis in magnesium-free-induced hippocampal neurons via the miR-142-5p/GABPB1 axis and protects against cerebral ischemia–reperfusion injury by enhancing neuronal proliferation and reducing apoptosis through the miR-186-5p/MDM4 pathway." (PMID 40725099, 2025).
clear cell carcinomas (1 paper, 2016). "Nevertheless, whether MDM2 and/or MDM4 are overexpressed in clear cell carcinoma remains to be established, along with whether MDM2 inhibitors are active against these forms of cancer." (PMID 27659536, 2016). "However, we found that MDM4 is expressed only in low levels in clear cell carcinomas." (PMID 27659536, 2016). "Therefore, MDM2 might be a more suitable target than MDM4 in clear cell carcinomas." (PMID 27659536, 2016).
dementia (1 paper, 2013). Loss of intellectual abilities interfering with an individual's social and occupational functions. "The expression of CCL-checkpoint and DNA damage response genes: MDM4, ATM and ATR was strongly upregulated and associated with progression of dementia (cognitive dementia rating, CDR), appearing as early as questionable or mild dementia (CDRs 0.5–1)." (PMID 23861893, 2013).
fibrosarcoma (1 paper, 2019). A malignant mesenchymal fibroblastic neoplasm affecting the soft tissue and bone. "Since MDM4 exerts a pro-apoptotic activity under stress conditions and its high levels have been associated with increased sensitivity to DNA damage and cisplatin treatment, we tested chemosensitivity of 3MCA-induced fibrosarcoma in WT and Mdm4Tg mice." (PMID 31547268, 2019). "In Mdm4 transgenic mouse, Mdm4 accelerates the formation of fibrosarcoma and increases tumor sensitivity to cisplatin as well, thus confirming in vivo Mdm4 dual mode of action." (PMID 31547268, 2019). "Since murine muscle expresses the estrogen receptor alpha (ERα) and high levels of the transgene Mdm4 and is sensitive to 3MCA tumorigenic activity, we induced fibrosarcoma in the dorsal part of hindlimb muscle." (PMID 31547268, 2019). "We show that in vivo Mdm4 is endowed both of tumorigenic potential by accelerating DNA-damage tumorigenesis, and anti-tumor activities by enhancing the sensitivity of fibrosarcoma to cisplatin and of thymocyte to radio-treatment." (PMID 31547268, 2019). "We observed that high levels of murine Mdm4 accelerate the formation of DNA-damage induced fibrosarcoma in a gender-independent manner." (PMID 31547268, 2019). "As a result, female mice bearing Mdm4-overexpressing fibrosarcoma are less sensitive to cisplatin treatment compared to male mice." (PMID 31547268, 2019). "These opposite consequences of MDM4 activity in response to two conditions of DNA damage (3MCA or Cisplatin) suggest that MDM4-mediated cell death poorly contributes to suppressing cell transformation at least in fibrosarcoma whereas it is relevant in response to chemotherapy." (PMID 31547268, 2019). "Given the lack of available antibodies to detect murine Mdm4 by IHC in fibrosarcoma, to ascertain whether this mechanism can occur in vivo, subcellular localization of Mdm4 was analyzed in thymocytes of Mdm4Tg mice." (PMID 31547268, 2019).
gastrointestinal stromal tumor (1 paper, 2015). "Several patients had multiple aberrations; a patient with wild-type gastrointestinal stromal tumor harbored five alterations (MDM4, MCL1, KIT, AKT3, and PDGRFA)." (PMID 26328274, 2015).
heart failure (1 paper, 2025). Inability of the heart to pump blood at an adequate rate to meet tissue metabolic requirements. "Notably, MDM4 loss exacerbates pressure overload-induced remodeling, while its preservation protects against stress-induced heart failure, underscoring its essential role in cardiomyocyte survival." (PMID 40813720, 2025).
Hyperinsulinemia (1 paper, 2015). An increased concentration of insulin in the blood. "Because hyperinsulinemia and IR are the crucial pathogenic signals for the development of NASH, in this study, we also found that insulin stimulation in vitro could lead to AKT, p-MDM2, MDM4 activation and impaired autophagy." (PMID 25826083, 2015).
leprosy (1 paper, 2018). Leprosy is a chronic infectious disease affecting primarily the skin and peripheral nervous system.
lymph node metastasis (1 paper, 2016). "The high expression level of MDM4 was significantly associated with age (P = 0.047), lymph node metastasis (LNM) (P < 0.001), pathological stage (P < 0.001), differentiation status (P = 0.001), and preoperative serum CA19-9 level (P < 0.001)." (PMID 27626496, 2016).
mesothelioma (1 paper, 2018). A usually malignant and aggressive neoplasm of the mesothelium which is often associated with exposure to asbestos.
nephrolithiasis (1 paper, 2024). The presence of a calculus in the pelvis of the kidney; this is most often composed of mineral salts and proteins. "In addition, GSVA results revealed that cluster 1 with higher expression of LAMP2 and MDM4, was enriched in lipid metabolism, amino acid metabolism, bile acid metabolism, and else, which can affect the risk of nephrolithiasis." (PMID 38536018, 2024). "Moreover, we partitioned a set of 29 nephrolithiasis samples into two distinct clusters based on the expression levels of LAMP2 and MDM4." (PMID 38536018, 2024).
nephrotoxic (1 paper, 2017). "To verify this, we examined the infiltration of inflammatory cells, and the expression of MDM-4 in VAN nephrotoxic AKI." (PMID 29022913, 2017).
Obesity (1 paper, 2019). Accumulation of substantial excess body fat. "The suggestion of targeting these axes to treat diseases associated with obesity is now being considered, i.e. by administering MDM4 inhibitors or targeting these MDM2 partnerships." (PMID 30689920, 2019).
oral squamous cell carcinoma (1 paper, 2024). "By GO and KEGG functional enrichment analysis of DEGs, we found that in OSCC (oral squamous cell carcinoma) MDM4 is closely related to secondary metabolic process, cornified envelope and iron ion binding." (PMID 38281029, 2024).
ovarian tumor (1 paper, 2017). "However, the frequency of Mdm2 or Mdm4 overexpression is low (2-4%) in ovarian tumor cells and cancer patients or non-existent in cis-Pt-resistant ovarian tumor cell lines." (PMID 28038466, 2017).
pancreatic ductal adenocarcinoma (1 paper, 2023). An infiltrating adenocarcinoma that arises from the epithelial cells of the pancreas. "The MDM4 SNP rs4951382 is coinherited with our tested SNPs, and the C-allele is linked to overexpression of RP11-430C7.5 in the lung, but little is known about RP11-430C7.5, except for its reported association with pancreatic ductal adenocarcinoma prognosis." (PMID 37345045, 2023).
renal carcinoma (1 paper, 2021). A carcinoma arising from the epithelium of the renal parenchyma or the renal pelvis. "One found that miR-33a inhibits cell growth in renal cancer by downregulation of MDM4 expression, and the other found that long non-coding RNA SNHG12 functions as a competing endogenous RNA to regulate MDM4 expression by sponging miR-129-5p in ccRCC." (PMID 34384473, 2021).
rheumatoid arthritis (1 paper, 2025). A chronic, systemic autoimmune disorder characterized by inflammation in the synovial membranes and articular surfaces.
Sepsis (1 paper, 2020). Sepsis is defined as life-threatening organ dysfunction caused by a dysregulated host response to infection. "Of the 317 sepsis-associated genes regulated by these DEMs, five (HIP1, GJC1, MDM4, IL6R, and ERC1) were designated as hub genes based on their degrees and other centrality measures (degree, betweenness, and closeness) from the significant modules." (PMID 33182754, 2020).
serous adenocarcinoma (1 paper, 2021). An adenocarcinoma that is characterized by the presence of papillary patterns and cellular budding. "To this purpose, we analyzed cell invasion through the matrigel of Empty Vector- and MDM4-expressing cells by transwell assay using both ID8 and OVCAR-3 cells another human EOC cell line derived from high-grade serous adenocarcinoma with mutant p5328." (PMID 34052831, 2021).
spinal muscular atrophy (1 paper, 2022). A motor neuron disease that affect the muscles, and characterized by muscle weakness and atrophy resulting from progressive degeneration and irreversible loss of the anterior horn cells in the spinal cord (i.e., lower motor neurons) and the brain stem nuclei.
T cell lymphoma (1 paper, 2024).
cancer (329 papers, 2009 to 2026). A tumor composed of atypical neoplastic, often pleomorphic cells that invade other tissues. "Alterations in MDM4, including gene amplification, have been observed in various cancers and its overexpression is associated with several tumor progression and poor prognosis." (PMID 41358317, 2025). "To date, 72 MDM2 and 8 MDM4 mRNA splice variants have been identified; some of these are highly expressed in cancers and associated with tumor growth in vivo." (PMID 39960347, 2025). "While RPL22 is mutated in cancer and clearly implicated in MDM4 splicing, what is the evidence regarding RPL5 and RPL11 in cancer?" (PMID 40427096, 2025). "In contrast, the increased inclusion of exon 6 causes the expression of full-length MDM4 in many human cancers." (PMID 38462618, 2024). "In this research, we analyzed the correlations between MDM4 expression and prognostic value, immune features, genetic mutation, or tumor related pathways in pan-cancer through multiple databases." (PMID 38281029, 2024). "The existence of the C minor allele (SNP rs4245739 A.C) in the MDM4 3′-UTR can reduce the cancer risk, and the metastasis progression." (PMID 36755123, 2023). "In breast malignancy, several SNPs, and mutations in MDM4 were reported to promote breast growth including the rs11801299 G > A polymorphisms." (PMID 36831624, 2023). "Evidences consistently suggested that MDM4 is overexpressed in various types of human cancer and are highly associated with tumorigenic processes including cell apoptosis, proliferation, metastasis, invasion, as well as the resistance to chemotherapy." (PMID 35778656, 2022). "Several studies observed the associations between single nucleotide polymorphisms (SNPs) in MDM2 and MDM4 genes and various cancers." (PMID 33669778, 2021). "SNP34091C is associated with increased cancer risk only in ER-negative breast cancer, suggesting that the presence of ERs interferes with MDM4 activity." (PMID 34307167, 2021). "Genetic studies have linked other SNPs in the MDM2 and MDM4 genes to increased cancer incidence or premature aging." (PMID 33406607, 2021). "MDM2 rs3730485 and MDM4 rs4245739 variants were studied in different types of cancer, together or in combination with one or with the other two mentioned variants, but from our knowledge, AML patients were not investigated." (PMID 32492903, 2020). "The relevance of MDM4 SNPs to disease is beginning to emerge as we discuss in this section in the context of cancer and viral susceptibility." (PMID 30689920, 2019).